GATA3 (GATA binding protein 3)
Diseases named in the same sentence as GATA3 in open-access papers (continued):
Sharing a sentence is not in itself a finding about the gene and the disease.
uveitis (3 papers, 2015 to 2018). An inflammatory process affecting a part of or the entire uvea. "Corticosteroids and CsA are the traditional drugs used for the treatment of uveitis, and a part of their beneficial effects may be caused by their ability to restore the aberrant methylation status of GATA3 and TGF-β." (PMID 28969068, 2017). "T-bet, GATA3, RORγt, and Foxp3 are master transcription factors for the important Th cell subsets of uveitis, including Th1, Th2, Th17, and Treg cells." (PMID 30254507, 2018). "Previous studies found the dysregulations of TBX21/GATA3 and Rorc/Foxp3 ratios in uveitis patients with neuro-BD20, suggesting that a dysregulated function of these T cell subsets may lead to immune imbalance, proliferation and activation of pathogenic CD4+ T cells subsequently leading to uveitis." (PMID 25873156, 2015). "An earlier study found that the ratio of Th1/Th17 cells was decreased in BD patients with uveitis, and another study reported an increase in the ratios of RORC/FOXP3 and TBX21/GATA3 in neuro-Behçet's disease, suggesting a dysregulation of Th1, Th2, Th17 and Tregs in this disease." (PMID 28969068, 2017). "Further studies should be performed to explore whether the abnormal DNA methylation of GATA3, IL-4 and TGF-β is also correlated with other uveitis entities." (PMID 28969068, 2017).
acinar adenocarcinoma (2 papers, 2025). "Following an innovative port-free single-site robot-assisted radical prostatectomy (pf-ssRARP) at our institution, immunohistochemical analysis (CK7/CK20/GATA3 positive, prostate-specific antigen (PSA) negative) confirmed the diagnosis of PHUCP combined with acinar adenocarcinoma." (PMID 41220953, 2025).
acute leukemia (2 papers, 2019 to 2024). A clonal (malignant) hematopoietic disorder with an acute onset, affecting the bone marrow and the peripheral blood. "GATA3 is a sensitive and specific marker for diagnosing acute leukemia with T-cell differentiation and may be a useful complement to the panel of immunophenotypic markers for the diagnostic evaluation of acute leukemia." (PMID 31074387, 2019).
apocrine tumors (2 papers, 2019 to 2025). "Further studies are needed to explore GATA3 and CK7’s role in diagnosing metastases of special cancer types, such as metaplastic, mucinous, and apocrine tumors." (PMID 31718619, 2019). "By definition, apocrine tumors express AR and GCDFP-15 while lacking ER, PR, BCL-2, and GATA3." (PMID 41293328, 2025).
autism (2 papers, 2021 to 2023). Persistent deficits in social interaction and communication and interaction as well as a markedly restricted repertoire of activity and interest as well as repetitive patterns of behavior. "We investigated the influence of 5-AIQ-treatment in BTBR T+ Itpr3tf/J (BTBR) mice as an autism model and used flow cytometry to assess the effect of 5-AIQ on FOXP3, Helios, GATA3, IL-9, IL-10 and IL-17A production by CXCR6+ and CD4+ T cells in the spleen." (PMID 33671196, 2021). "As such, a specific alteration of T clones in PBMCs of autism patients versus typically developing children had already been observed in previous studies: a reduction in Foxp3 (T reg) and an increase in STAT3 and ROR γ t (Th17), T-bet (Th1) and GATA-3 (Th2) were noted." (PMID 37588589, 2023).
B-cell acute lymphoblastic leukemia (2 papers, 2016 to 2022). A neoplasm of lymphoblasts committed to the B-cell lineage, typically composed of small to medium-sized blast cells. "Genome-wide association studies have revealed that inherited genetic variation in GATA3 is associated with susceptibility to developing B cell acute lymphoblastic leukemia and the B cell leukemia risk allele is associated with increased GATA3 expression." (PMID 27588406, 2016).
bladder (2 papers, 2014 to 2021). "None of SCC of the urinary bladder is GATA-3 positive by immunohistochemistry staining." (PMID 25042800, 2014).
breast disease (2 papers, 2014 to 2024). "GATA3 is also thought to be often positive in primary breast disease." (PMID 39943990, 2024).
cardiac arrest (2 papers, 2013 to 2016). Cessation of breathing and/or cardiac function. "Upon cardiac arrest, an abnormal stress response occurs and causes the change of transcription factor T-bet/GATA-3, resulting in the imbalance of Th1/Th2." (PMID 28018242, 2016). "In this study, the effects of SFI on the expression of T-bet/GATA-3 and its potential mechanisms causing the shift of T cells from Th2 to Th1 on postresuscitation lung injury were examined in a porcine model of cardiac arrest." (PMID 23573129, 2013). "This has also been confirmed by a porcine model of cardiac arrest that lowers GATA-3 and T-bet levels, which alters the drifting Th1/Th2 cells and causes the immune imbalance of myocardial tissue after cardiopulmonary resuscitation (CPR)." (PMID 28018242, 2016).
Chlamydia infection (2 papers, 2013 to 2024). "Although the transcription factor GATA3 regulates Th2 development, Gata3 null mutant mice are embryonic lethal, thus we examined Chlamydia infection of STAT6-deficient mice which lack Th2 development." (PMID 38166152, 2024). "Paraffin-embedded endometrial tissues from uninfected women and women with extantendometrial Chlamydia infection (but no other identified genitaltract infection) were stained with polyclonal antibodies detecting GATA-3 or T-bet(both Abcam) and/or a monoclonal antibody detecting CD4 (Dako)." (PMID 23555586, 2013).
chronic asthma (2 papers, 2022 to 2023). An asthma that is characterized by the development of persistent airway inflammation and recurrent attacks of breathlessness and wheezing, which vary in severity and frequency. "Such as olaparib significantly reduces the protein expression of STAT‐6 and GATA‐3, inhibits the inflammasome signaling, and reduces the remodeling characteristics associated with chronic asthma in mice." (PMID 37904699, 2023). "Moreover, the HSP70/CD80 DNA vaccine has been found to reduce airway remodeling in chronic asthma via regulating the transcription factors T-bet and GATA-3, which are essential for Th1 and Th2 differentiation." (PMID 36553658, 2022).
classic Hodgkin lymphoma (2 papers, 2022 to 2024). Classical Hodgkin lymphoma (CHL) is a B-cell lymphoma characterized histologically by the presence of large mononuclear Hodgkin cells and multinucleated Reed-Sternberg (HRS) cells. "GATA3 is a transcription factor involved in T-cell maturation and has been previously shown to be aberrantly overexpressed in malignant Hodgkin and Reed–Sternberg (HRS) cells of classical Hodgkin lymphoma (cHL)." (PMID 38534975, 2024).
clear cell renal carcinoma (2 papers, 2017 to 2020). A malignant epithelial neoplasm of the kidney characterized by the presence of lipid-containing clear cells within a vascular network. "Another study confirmed that the GATA3 gene was more strongly methylated in clear cell renal carcinoma (ccRCC) and was partly due to a loss of the expression of this gene." (PMID 28969068, 2017). "Taken together, our findings suggest that the IL6/STAT3 pathway plays a crucial role in the normal fibroblast-enhanced clear-cell renal cell carcinoma metastasis, while GATA3 may mitigate this effect by inhibiting IL6/STAT3 signaling." (PMID 31636361, 2020).
colorectal adenocarcinoma (2 papers, 2017 to 2023). The most common type of colorectal carcinoma. "GATA3 is negative in colorectal adenocarcinoma and therefore is useful to distinguish primary genital EMPD from secondary EMPD due to colorectal adenocarcinoma." (PMID 28693610, 2017).
Crohn disease (2 papers, 2020). A gastrointestinal disorder characterized by chronic inflammation involving all layers of the intestinal wall, noncaseating granulomas affecting the intestinal wall and regional lymph nodes, and transmural fibrosis. "The results of this study indicated that GATA3 has a key role in CD pathogenesis and could be a possible drug target or diagnostic biomarker for Crohn’s disease." (PMID 33585004, 2020). "Among the 81 queried DEGs related to Crohn’s disease, 7 genes (IL-7, GATA3, CD28, CD5, TXN, ETS-1, and CCR7) were introduced as dysregulated genes." (PMID 33585004, 2020). "Through network analysis, we can introduce IL-7, GATA3, TXN, ETS-1, CCR7, CD28, and CD5 as Crohn’s disease-related critical genes and possible biomarker panel." (PMID 33585004, 2020).
cyst (2 papers, 2023 to 2024). A sac-like closed membranous structure that may be empty or contain fluid or amorphous material. "The cyst epithelia stained intensely positive for human bone marrow endothelial marker-1 (HBME-1) and cytokeratin 5/6, and negative for paired box protein 8 (PAX8) and GATA binding protein 3 (GATA3)." (PMID 36862889, 2023).
dementia (2 papers, 2020 to 2024). Loss of intellectual abilities interfering with an individual's social and occupational functions. "Considering the beneficial role of GATA3 in regulating AD pathology via transcriptional activation of HLA61, thereby GATA3 serves as a promising target for managing dementia-associated conditions." (PMID 39768217, 2024).
developmental delay (2 papers, 2024 to 2025). "Moreover, other risk genes for developmental delay, such as BRD3, KBTBD7, and GATA3, also peaked during this stage, whereas SOX2 displayed high expression in a later lineage." (PMID 39363111, 2024). "Similarly, facial dysmorphism, growth disturbances, and developmental delay observed in individuals with larger 10p deletions were not present in patients with point mutations (SNVs) in the GATA3 gene, which also indicates the involvement of other genes." (PMID 40686918, 2025).
DiGeorge syndrome (2 papers, 2021 to 2025). "Microdeletions of chromosome 10p14, affecting, among others, the GATA3 gene, are defined as DGS/VCFS complex 2 (DiGeorge syndrome/velocardiofacial syndrome complex 2)." (PMID 40869914, 2025).
endometrial tumors (2 papers, 2021). "Furthermore, 12 of 16 positive cases displayed high-grade or ambiguous cytologic features, raising the possibility that poorly differentiated endometrial tumors may express GATA3 not due to lineage but rather due to gain of function mutations." (PMID 33986807, 2021).
erosive gastropathy (2 papers, 2020 to 2021). "Esophagogastroduodenoscopy revealed a non-bleeding erosive gastropathy, which was biopsied and found significant for a poorly differentiated, GATA3-positive SRCC." (PMID 33732425, 2021).
gastroesophageal reflux disease (2 papers, 2023 to 2024). A chronic disorder characterized by reflux of the gastric and/or duodenal contents into the distal esophagus. "Study demonstrated that enriched genes including IL1B, CXCR1, FFAR4, VIP (vasoactive intestinal peptide), and GATA3 have been identified as a key candidate genes in patients with gastroesophageal reflux disease." (PMID 38137330, 2023).
Granuloma (2 papers, 2013 to 2023). A compact, organized collection of mature mononuclear phagocytes, which may be but is not necessarily accompanied by accessory features such as necrosis. "To address whether cells can co-express T-bet and GATA-3 during a strongly Th2-biased response, we directly immunized and challenged mice with S. mansoni eggs, inducing type-II granulomas in the lung." (PMID 23976880, 2013).
HIV-1 infection (2 papers, 2012 to 2023). The type species of lentivirus and the etiologic agent of acquired immunodeficiency syndrome (AIDS). "To further explore the cytokine profiles during HIV-1 infection, we measured the expression of the transcription factors reported to be associated with different T-cell lineages, i.e. T-bet, GATA-3, Foxp3 and ROR-γt that are expressed by Th1, Th2, Treg and Th17 respectively." (PMID 22276176, 2012). "This is contrary to the reported findings that GATA3 is most abundantly expressed in T lymphocytes, a cellular target for human immunodeficiency virus type 1 (HIV-1) infection and replication." (PMID 37568838, 2023).
Hyperglycemia (2 papers, 2015 to 2025). An increased concentration of glucose in the blood. "Since our model could be hyperinsulinemic due to prolonged state of hyperglycemia, as previously reported, the alterations of Gata3 (Th2) and Foxp3 (Treg) expression found in the present study could be indirectly induced through an insulin-dependent pathway." (PMID 26207186, 2015). "We examined the differentiation of CD4+ lymphocytes by measuring the master genes, including the Tbx21 for Th1, the Rorc for Th17, Gata3 for Th2, and Foxp3 for Treg to evaluate whether hyperglycemia and endotoxemia synergistically modulate the balance between pro- and anti-inflammatory responses." (PMID 26207186, 2015). "In chondrocytes, hyperglycemia upregulated PTEN and downregulated GATA3 expression." (PMID 41476995, 2025). "In the analysis of the transcriptional factors of CD4+ T lymphocytes, the interaction between endotoxemia and hyperglycemia was not statistically significant in the effect on Tbx21 or Rorc, but was in the effect on Gata3 and Foxp3." (PMID 26207186, 2015).
Hypertension (2 papers, 2019 to 2024). The presence of chronic increased pressure in the systemic arterial system. "CYP3A4, APOA2, PPARG, ALOX, and CYP4F2, proteins related to lipid homeostasis affect the occurrence of hypertension, and PTGER2, ALOX5, LTF, ITGB, and GATA3 relate to the inflammatory and immune response in glomeruli." (PMID 30809144, 2019).
leprosy (2 papers, 2018 to 2019). Leprosy is a chronic infectious disease affecting primarily the skin and peripheral nervous system. "When comparing leprosy patients to HHC, 16 genes showed significantly different expression for leprosy patients (increased: FCGR1A, IL6, IL15, LRKK2, MBP, MSR1, PACRGv1, TLR1, TLR4; decreased: CAMTA, CD3E, CTLA4, CXCL13, GATA3, LAG3, TFGB)." (PMID 31784594, 2019).
liposarcoma (2 papers, 2023 to 2025). A usually painless malignant tumor that arises from adipose tissue. "We report a pleomorphic liposarcoma, epithelioid variant, in an 88-year-old man, with tricky-positive staining for GATA3." (PMID 37007224, 2023). "This study aimed to investigate the gene expression profiles of SOX9, GATA3, and GATA4 in liposarcoma subtypes and to assess their associations with clinicopathological parameters." (PMID 41303462, 2025). "Notably, although SOX9, GATA3, and GATA4 have been previously implicated in various malignancies, this is the first qRT-PCR-based study to systematically quantify their expression in human liposarcoma tissue." (PMID 41303462, 2025). "To assess the prognostic relevance of SOX9, GATA3, and GATA4 gene expression levels on overall survival in liposarcoma patients, we performed univariate Cox proportional hazards regression using continuous RQ values as covariates." (PMID 41303462, 2025). "This study provides qRT-PCR-based evaluation of SOX9, GATA3, and GATA4 gene expression in liposarcomas, revealing consistent overexpression patterns across multiple histological subtypes." (PMID 41303462, 2025). "Despite progress in molecular diagnostic tools, the current literature offers limited data regarding the expression profiles of transcription factors such as the Sex-determining region Y-box 9 (SOX9), GATA3, and GATA4 in liposarcoma." (PMID 41303462, 2025). "In this study, we conducted a comprehensive molecular analysis of SOX9, GATA3, and GATA4 gene expression in a cohort of 42 liposarcoma cases using quantitative real-time PCR." (PMID 41303462, 2025). "Boxplot analysis confirmed substantial interindividual variability in the expression levels of SOX9, GATA3, and GATA4 across the 42 analyzed liposarcoma cases." (PMID 41303462, 2025). "The relative expression values (RQ) of SOX9, GATA3, and GATA4 were evaluated in 42 liposarcoma cases." (PMID 41303462, 2025). "Considering these knowledge limitations, the present study aims to evaluate the relative expression levels (RQ) of SOX9, GATA3, and GATA4 in a series of human liposarcoma samples, using a comparative molecular approach based on quantitative real-time PCR." (PMID 41303462, 2025). "Collectively, these findings underscore that the altered expression of SOX9, GATA3, and GATA4 observed in liposarcoma may reflect dysregulated MSC differentiation mechanisms and impaired adipogenic transcriptional control." (PMID 41303462, 2025). "While exploratory, this shared miRNA regulatory signature suggests that GATA3 and GATA4 may participate in a coordinated transcriptional module in liposarcoma." (PMID 41303462, 2025). "Collectively, these observations raise the hypothesis that GATA3 and GATA4 act in parallel or complementary fashion to support phenotypic adaptability or dedifferentiation programs in liposarcoma." (PMID 41303462, 2025). "Together, these data justify investigating SOX9, GATA3, and GATA4 within the mesenchymal context of liposarcoma, where they may cooperatively contribute to aberrant lineage maintenance and tumor progression." (PMID 41303462, 2025). "This raises the possibility that SOX9, GATA3, and GATA4 are not merely subtype-specific markers but may instead reflect a broader oncogenic pathway active across diverse liposarcoma variants." (PMID 41303462, 2025).
Lymphadenopathy (2 papers, 2016 to 2022). Enlargement (swelling) of a lymph node. "GATA3 is the master transcription factor for Th2 differentiation, and IL-4 induces its expression.Mice with Treg cell specific GATA3 deletion develop autoimmune symptoms of splenomegaly and lymphadenopathy at the age of 16 weeks." (PMID 35898499, 2022). "The majority of p18−/−;Gata3+/− mice displayed various degrees of lymphadenopathy whereas no enlargement of the thymus, spleen nor lymph nodes were detected in WT and Gata3+/− mice at a similar age." (PMID 27588406, 2016).
lymphoepithelioma (2 papers, 2022 to 2023). "The tumor cells were positive for cluster of differentiation (CD) 10, cytokeratin (CK) AE1/AE3, cytokeratin 7, cytokeratin 20, cytokeratin 34βE12, GATA binding protein 3 (GATA3), and protein‐63 (p63), which are markers of lymphoepithelioma‐like carcinomas." (PMID 36052737, 2022).
mediastinal tumours (2 papers, 2024 to 2025). "HN-PG and the suspected non-chromaffin mediastinal tumours had low expression of the chromaffin cell marker CARTPT24, neural transcriptional regulators (TFAP2B, TOX3, GATA3, POU4F, NEUROG2, PAX2), HOX genes (HOXA1-10, HOXB4, HOXB6-9, HOXC4-HOXC13), and the long non-coding RNA HOTAIR." (PMID 40097403, 2025). "HN-PG and the suspected non-chromaffin mediastinal tumours had low expression of the chromaffin cell marker CARTP24, neural transcriptional regulators (TFAP2B, TOX3, GATA3, POU4F, NEUROG2, PAX2), HOX genes (HOXA1–10, HOXB4, HOXB6–9, HOXC4-HOXC13), and the long non-coding RNA HOTAIR." (PMID 38978571, 2024).
meningitis (2 papers, 2014 to 2017). A disorder characterized by acute inflammation of the meninges of the brain and/or spinal cord. "Neuropathologically, GATA3-tg mice had decreased levels of meningitis and demyelination in the spinal cord, compared with wild-type mice." (PMID 24463292, 2014). "Histologically, GATA3-tg mice had decreased levels of meningitis and demyelination in the spinal cord, and anti-inflammatory cytokine profiles immunologically, however both groups developed similar levels of MOG-specific lymphoproliferative responses." (PMID 24463292, 2014). "In the spinal cord, 1 week p.i., both wild-type mice and Gata3-tg mice developed meningitis and perivascular cuffing, but not demyelination, and had similar pathology scores." (PMID 28874814, 2017).
mesonephric adenocarcinoma (2 papers, 2017 to 2025). An adenocarcinoma of the cervix or the vagina arising from mesonephric remnants. "Mesonephric adenocarcinoma characteristically expresses mesonephric markers such as GATA3, TTF1, and PAX2, while lacking hormone receptor expression." (PMID 40647429, 2025).